ZNF702P (zinc finger protein 702, pseudogene)
Description:
May be involved in transcriptional regulation.
Synonyms: FLJ12985; formerly ZNF702
Gene: Transcribed processed pseudogene on chromosome 19 (52,968,910 to 52,970,875, reverse strand). Ensembl gene ENSG00000242779.
Subcellular location: Nucleus
Diseases named in the same sentence as ZNF702P in open-access papers:
ZNF702P is named in the same sentence as 3 diseases in open-access papers, as found by Europe PMC text mining. Sharing a sentence is not in itself a finding about the gene and the disease. The quoted sentences say what the papers report.
lung adenocarcinoma (1 paper, 2022). A carcinoma that arises from the lung and is characterized by the presence of malignant glandular epithelial cells. "ZNF259P1 was significantly correlated with the tumor size of primary lung adenocarcinomas, while ZNF702P was found to be upregulated after BCL2L10 knockdown in two ovarian cell lines." (PMID 37521848, 2022).
ZNF702P also shares sentences with these, for which no sentence is quoted: osteoporosis (1 paper); tumor (1).